RN7SL201P (RNA, 7SL, cytoplasmic 201, pseudogene)
Gene: Miscellaneous RNA gene on chromosome 2 (81,967,079 to 81,967,374, forward strand). Ensembl gene ENSG00000242118.
Homologues: Orthologues: chimpanzee Metazoa_SRP (98% identical), macaque Metazoa_SRP (92% identical). Paralogues in human: RN7SL1 (81% identical), RN7SL3 (81% identical), RN7SL126P (81% identical), RN7SL2 (81% identical), RN7SL230P (80% identical), RN7SL448P (79% identical), RN7SL743P (79% identical), RN7SL88P (79% identical), RN7SL122P (79% identical), RN7SL45P (79% identical), RN7SL664P (79% identical), RN7SL218P (78% identical), and 703 more.